VCAM1 (vascular cell adhesion molecule 1)
Diseases named in the same sentence as VCAM1 in open-access papers (continued):
Sharing a sentence is not in itself a finding about the gene and the disease.
tumor (continued). "Moreover, we confirmed that tumor VCAM1 reduced CDC42 expression in human CD8 T cells as well, and that led to impaired IFN-γ production." (PMID 38332012, 2024). "Then, the AMDs were incubated with the VCAM‐1 positive tumor cells." (PMID 38484186, 2024). "Notably, interfering with macrophage-iNKT cell interactions in addition to knocking down Vcam1 in MC38 tumor cells further enhanced anti-tumor efficacy of iNKT cells." (PMID 38332012, 2024). "Sensitive, sonic hedgehog (Shh) pathway-driven BCC epithelium arises through the ability to recruit and instruct TREM2 + VCAM1+ myeloid cells into a self-propagating phenotype that allows mutual proliferation and tumor growth with a dearth of effector lymphocytes present in the local environment." (PMID 39289380, 2024). "Interestingly, circulating tumor cells can upregulate ICAM-1 or VCAM-1 expression to recruit and retain myeloid cells on them and utilize those immune cells for metastasis." (PMID 38786066, 2024). "Additionally, we confirmed that interfering with the VCAM1-CD49d signaling in these B16F10 tumor models augmented IFN-γ production in intratumoral iNKT cells, despite no influence on cell infiltration." (PMID 38332012, 2024). "Similar to luminal cluster 2 in primary tumour, cluster 3 in lung mets, was enriched in a proliferation gene signature (Ran, Cks1b, and Cks2), whereas cluster 2 (homologous to cluster 3 in primary tumour), expressed a mesenchymal-like gene set (Col18a1, Vcam1, Col1a1, Vim, Sparc)." (PMID 38238426, 2024). "Furthermore, immune-excluded tumors express higher levels of endothelial adhesion molecules (AMs) such as vascular cell adhesion molecule 1 (VCAM-1) at the tumor periphery." (PMID 39107856, 2024). "Notably, knockdown of tumor Vcam1 increased CDC42 expression in both GFP+ transferred and GFP- host iNKT cells in tumors." (PMID 38332012, 2024). "Additionally, we found that knockdown of Vcam1 in MC38-mCherry tumor cells recovered motility of intratumoral GFP+ transferred iNKT cells, as indicated by longer migration trajectories, stochastic directions, higher velocities, and longer displacement lengths." (PMID 38332012, 2024). "Interestingly, anti-ANGPT2 treatment improved vascular integrity and decreased AM discrepancy, especially VCAM-1 and L-selectin, which released sequestered T cells from the periphery into the central tumor areas and reversed the immune-excluded phenotype." (PMID 39107856, 2024). "Vascular cell adhesion molecule 1 (VCAM-1) is involved in tumor angiogenesis." (PMID 38516703, 2024). "To this end, using an MRI contrast agent based on microparticles of iron oxide (MPIO) and targeted to VCAM-1, we have previously demonstrated that VCAM-1 provides a sensitive and specific endothelial biomarker of early brain metastasis, as well as improving detection of the tumour-brain interface." (PMID 39000268, 2024). "Furthermore, the elevated levels of VCAM1 and TEK in HCC patients suggest their role in tumor progression and potential as diagnostic markers." (PMID 39286634, 2024). "Although not directly linked to fluid shear stress, tumor-associated endothelial cells down-regulate genes related to immune extravasation, such as ICAM-1 and VCAM-1, in many cancers, further contributing to a less permissive environment for NK cell extravasation to the tumor tissue." (PMID 38671750, 2024). "Several studies have correlated VCAM-1 expression and function with tumor angiogenesis." (PMID 39596815, 2024). "The results represented a tendency almost consistently similar to the primary tumor-bearing mouse model, which further verified that Suc could efficiently inhibit VCAM-1 expression and Dox enhanced the effects of Suc." (PMID 36839671, 2023). "Induction of ICAM-1, VCAM-1, and E-selectin in ECs has been shown to promote tumor cell adhesion." (PMID 37124539, 2023).
tumor (continued). "Particularly within the tumor bulk, even if in lower number, VCAM1+ vessels were still significantly closer to both subsets of CD8+ T‐cells, suggesting that an inflamed vessel phenotype maintain a more proficient crosstalk with infiltrated TILs, even in the absence of STING." (PMID 38009521, 2023). "In addition to LFA-1, integrin VLA-4 (α4β1 integrin) expression of T cells, which binds to vascular cell adhesion molecule-1 (VCAM1) on endothelial cells, also controls effector T cell tumor infiltration." (PMID 37605139, 2023). "In addition, macrophages can achieve active tumor targeting owing to the interaction between α4 integrins on macrophage membranes and VCAM-1 on tumor cell membranes." (PMID 37514008, 2023). "Our results showed that VCAM1 was downregulated in the tumor-resected group compared to the tumor-bearing group, which may imply that the resection eliminated VCAM-1-expressing tumor cells." (PMID 36718454, 2023). "Moreover, mRNA detection results of tumor tissues showed that vitamin C treatment significantly decreased the expression of VCAM-1, Vimentin, CD31 and CD44." (PMID 37283769, 2023). "It was reported that Suc could selectively and efficiently inhibit VCAM-1 expression, which indicates that Suc could be a promising drug for inhibiting the metastasis of tumor cells." (PMID 36839671, 2023). "A similar positive correlation was found with VCAM1+ vessel counts within the tumor bulk." (PMID 38009521, 2023). "Thus, after VCAM-1 knocking-down in tumor cells or the depletion of macrophages, the pro-tumor effect of CAFs is partly abolished." (PMID 36982677, 2023). "VCAM-1 can also promote tumour cell invasion and metastasis." (PMID 36979820, 2023). "We acknowledge that this study focuses entirely on the role of Vcam1 in iCCA tumor cells." (PMID 36828890, 2023). "Additionally, radiation therapy can increase the expression of adhesion molecules like intercellular adhesion molecule-1 (ICAM-1) and vascular cell adhesion molecule-1 (VCAM-1) on tumor endothelial cells." (PMID 38162672, 2023). "Other integrin-mediated tumor cell adhesion includes αVβ1 or αVβ3 on tumor cells with L1 cell adhesion molecular (L1CAM) on the endothelium and α4β1 on tumor cells with vascular cell adhesion molecule-1 (VCAM1) on the endothelium, further allowing CTCs to extravasate and form distant metastases." (PMID 37046617, 2023). "However, quantification of serum sVCAM-1 levels is currently unable to distinguish between sVCAM-1 derived from endothelial cells or tumor cells and VCAM-1 released from angiogenic lymphatic vessels." (PMID 37357306, 2023). "Furthermore, immunohistochemistry (IHC) demonstrated that BF-TK/GCV reduced the expression of HIF−1α, mTOR, NF-κB1-p105, VCAM1, MMP13, CXCL12, ATG16, and CEBPB, which were associated with tumor metastasis." (PMID 37511481, 2023). "Additionally, we found a proliferative TREM2+VCAM1+ macrophage primarily residing in the LT region (which we termed SCAMs) that possesses the surprising capacity to directly regulate LY6D- tumor epithelial proliferation via the secretion of OSM ligand." (PMID 37164949, 2023). "In addition, neutral sphingomyelinase 2 (nSMase2)-dependent EC activation has been shown to express chemokines, CX3CL1 and CXCL10, as well as the adhesion molecule VCAM1, to promote T cell migration into the tumor bed." (PMID 36901858, 2023). "Similarly, galectin-9 also acts as a competitive inhibitor by blocking the VCAM1-α4β1 interactions, thereby reducing tumor cell adhesion to the vascular endothelium and consequent tumor cell extravasation and metastasis." (PMID 36873388, 2023). "Compared with the research above, this platform showed homogenous tumor targeting abilities in vitro via α4 integrin-VCAM-1 interaction and markedly enhanced multitarget capability in a lung metastasis model in vivo owing to the participation of tumor cell membranes." (PMID 37654704, 2023). "VCAM-1 expression is highly correlated with tumor cell adhesion and extravasation." (PMID 37773178, 2023).
tumor (continued). "On the other hand, α4 and β1 integrins on macrophage cell membrane could actively bind to the vascular cell adhesion molecule-1 (VCAM-1) on cancer cells, endowing them with tumor-targeting ability." (PMID 37626073, 2023). "Alternatively, VCAM-1 in the endothelium also binds to monocytes and neutrophils that may bind tumor cells." (PMID 37773178, 2023). "On the other hand, VEGF inhibits the adhesion of lymphocytes to endothelial cells through intercellular adhesion molecule-1 (ICAM-1), vascular cell adhesion molecule-1 (VCAM-1), and Fas Ligand (FasL), thereby affecting the infiltration of T cells into the tumor tissue." (PMID 36936932, 2023). "However, interestingly, we found that Vcam1 levels dropped significantly in tumor cells collected from the 6-week SpheroidT:pMF 2.5D coculture." (PMID 36828890, 2023). "Finally, immunofluorescence assays were performed to evaluate VCAM-1 expression on B16F10 cells of the tumor tissues after different treatments." (PMID 36839671, 2023). "Furthermore, a surface of the tumor endothelium cells expresses glycoprotein known as vascular cell adhesion molecule-1 (VCAM-1), which is actively involved in the process of angiogenesis." (PMID 37629007, 2023). "For instance, miR-374a is lower in the center of tumor mass compared to the edges and may be associated with differential and opposite expression of its angiogenic targets VEGFA and vascular cell adhesion molecule 1(VCAM1) in tumor mass." (PMID 37583933, 2023). "In summary, using PLGA nanoparticles loaded with the VCAM-1 inhibitor succinobucol and the chemotherapeutic doxorubicin provides a promising drug nano-delivery strategy combining anti-primary tumor therapy and anti-lung metastasis therapy for metastatic malignant tumors." (PMID 36839671, 2023). "Furthermore, localisation and activation of NK cells are mediated by the lymphocyte-associated protein LFA-1 and vascular lymphocyte function-associated protein VLA-4, as well as the recognition of ICAM1 and VCAM1 on tumour endothelial cells." (PMID 36077754, 2022). "Moreover, endothelial VCAM-1 was markedly upregulated at the tumor margins in both models, with negligible expression evident in normal brain tissue, as previously reported." (PMID 35312755, 2022). "We demonstrate that TNFα increased VCAM-1 expression in the tumor tissue, which could be involved in the intra-tumoral stromal and endothelial invasion." (PMID 36290384, 2022). "Vascular cell adhesion molecule 1 (VCAM1) induction in endothelial cells can regulate tumor progression, provide angiogenic factors, promote neutrophil infiltration and tumor cell adhesion to the endothelium, and promote metastasis by sustaining vascular Notch1 signaling." (PMID 35464435, 2022). "In endothelial cells, Notch1 ICD activity in human carcinomas and melanoma orchestrated tumor progression and metastasis through increasing expression of chemokines and the adhesion molecule VCAM1, which promotes neutrophil infiltration and tumor cell adhesion." (PMID 35330188, 2022). "However, although the overexpression of factors such as G-CSF favoured circulating tumour and white blood cells cluster, the inhibition of vascular cell adhesion molecule 1 (VCAM1) or lymphocyte antigen 6 complex locus G6D (Ly-6G) prevented this association." (PMID 35406451, 2022). "Such molecules, including TNF-α and IL-1, play an important role for tumor progression because their upregulation triggers the expression of adhesion molecules (e.g., e-selectin and vascular cell adhesion molecule-1) on endothelial cells, which act as mediators for tumor growth." (PMID 36077144, 2022). "It was reported that VCAM-1 was aberrantly expressed in tumor cells, and it could mediate distinct tumor-microenvironment interactions in leukocyte-rich microenvironments of the lungs to facilitate their metastasis." (PMID 36110525, 2022).
tumor (continued). "HIF-1α could directly upregulate ANGPTL4 and promoted tumour metastasis by activating the vascular cell adhesion molecule-1/integrin β1 signalling axis." (PMID 36050447, 2022). "Furthermore, VCAM1 plays an important role in anti-tumor T cell responses and T cell infiltration into tumors." (PMID 36221114, 2022). "Since CD44 is known to bind VCAM-1, which decreases tumor growth, it is possible that Quercetin could reduce the expression of VCAM-1 and therefore endothelial activation." (PMID 35336985, 2022). "Accumulating data indicate that IL-1β activates 2 major downstream effectors, the NF-κB and MAPK pathways, to stimulate the expression of adhesion molecules such as ICAM1 and VCAM1 in diverse cell types including tumor cells, thereby amplifying and sustaining responses to IL-1β." (PMID 36264639, 2022). "CRT also increases expression of intercellular adhesion molecule (ICAM)-1 and vascular cell adhesion molecule (VCAM)-1 on tumour endothelial cells via nuclear factor kappa-light-chain-enhancer of activated B cells (NF-κB) activity, thereby improving anti-tumour immune responses." (PMID 36497148, 2022). "Next, we analyzed whether the BZM-mediated reduction of E-selectin, ICAM-1, and VCAM-1 has a functional consequence for the adhesion of human tumor cells to HUVECs in laminar flow adhesion assays." (PMID 35031433, 2022). "Similarly, VCAM-1 expression was significantly greater in the tumor rim for both models (Friedman test, P < 0.001 for both models), with negligible VCAM-1 expression evident in the contralateral striatum." (PMID 35312755, 2022). "In addition, they can also stimulate the expression of the vascular cell adhesion molecule-1 (VCAM1), which leads to the attraction of MBC cells to ECs and promotes the interactions between tumor cells and ECs, which increases the risk of cancer metastasis." (PMID 36291773, 2022). "The VEGF-C enhances the formation of tumor lymphatic vessels surrounding tumors and activates the integrin α4β1 on the endothelium of the tumor lymphatic vessels which interacts with vascular cell adhesion molecule 1 (VCAM-1) to promote cancer cell migration and LN metastasis." (PMID 35265612, 2022). "Previous studies have shown that tumor cell-induced neutrophil ETs could stimulate immune cells to release inflammatory cytokines, including IL-1, IL-6, ICAM-1, VCAM-1, and E-selectin, leading to tumor growth." (PMID 36325339, 2022). "Furthermore, in vivo use of anti-VCAM1 neutralizing antibodies also significantly inhibited tumor growth with enhanced T cell infiltration." (PMID 35832090, 2022). "On this basis, we hypothesized that application of VCAM-1–targeted MRI may enable more sensitive delineation of the tumor-brain interface." (PMID 35312755, 2022). "The aim of this study was to determine whether microvascular inflammation can be targeted to better delineate the tumor-brain interface through vascular cell adhesion molecule-1 (VCAM-1)-targeted MRI." (PMID 35312755, 2022). "Due to adverse effects or drug resistance in long-term bevacizumab-treated patients, new targets may be identified, with VCAM-1 targeting a possible strategy to inhibit tumor metastasis." (PMID 33800796, 2021). "Within these vessels, tumor endothelial cells (ECs) exhibit an activated or pro-inflammatory state characterized by increased expression of surface adhesion molecules such as VCAM1 and ICAM1, which facilitate the recruitment and attachment of leukocytes to the vessel wall." (PMID 33853689, 2021). "Vascular cell adhesion molecule-1 (VCAM-1) is involved in tumor cell adhesion and metastasis, and matrix metalloproteinases (MMPs) are responsible for the angiogenesis and metastasis, RGD ligands are another frequently used target and the recognition is via αvβ3 integrin." (PMID 34805129, 2021).
tumor (continued). "In a subpopulation of MDA-MB-231 breast tumor cells that showed lack of ability to form bone metastases in vivo, authors could show that the ability to form progressive bone metastatic lesions was accompanied by increased expression of VCAM-1 by tumor cells." (PMID 33805598, 2021). "Thus, integrin α4β1 and αvβ3 with their respective ligands VCAM-1 and osteopontin offer potential targets for therapeutic development within the osteoblast-osteoclast-tumor interface." (PMID 33805598, 2021). "VCAM1 is expressed by ECs and bound by tumor cells expressing integrin alpha4beta1 (VLA4)." (PMID 34073394, 2021). "In addition, type II IFN-γ was also released to upregulate the MHC class I and vascular cell adhesion molecule 1 (VCAM1) expression to enhance the tumor antigen presentation." (PMID 33922480, 2021). "Besides E-selectin, vascular adhesion molecule-1 (VCAM1) is crucial for leukocyte and tumor cell transmigration." (PMID 34073394, 2021). "Macrophage-expressed integrin α4β1 has been reported to interact with tumor cell-expressed vascular cell adhesion molecule 1 (VCAM-1), resulting in sustained survival of these newly extravasated tumor cells and elevated local macrophage activity within distant metastatic sites." (PMID 34884995, 2021). "Patient-derived CAFs can induce the adhesion and enrichment of monocytes by upregulating the expression of VCAM1 and the secretion of IL-8 and promote the recruitment of M2 macrophages into the tumour microenvironment, which together inhibit the function of NK cells." (PMID 34717544, 2021). "High VCAM1 levels in tumor cells interact with osteoclast-expressed α4β1 integrin, which may recruit osteoclast precursor cells, initiate the osteoclast process, and ultimately induce the osteolytic clinical manifestations of bone metastasis." (PMID 33869189, 2021). "This analysis showed that genes representing T-cell activation and tumor-killing including Ifng, Vcam1, Rgs1, and Il2rb, had higher expression levels, whereas T-cell exhaustion genes such as Tim-3, Ccl3, Rgs2, and Cd6f3, had lower expression levels in Ogr1−/− mice than that in the WT mice." (PMID 34158625, 2021). "In kidney and pancreatic tissues, the forced overexpression of LTα promotes lymphoid aggregate formation (containing T cells, B cells, and APCs) and tumor vascular reprograming, as indicated by increased expression of VCAM-1, ICAM-1, MAdCAM, and PNAd on VEC/HEV." (PMID 34054879, 2021). "In summary, our study demonstrates that VCAM1 improves tumor progression in CRC." (PMID 32793471, 2020). "Finally, anti-angiogenic drugs normalize tumor vasculature and induce the upregulation of the leukocyte adhesion molecules ICAM1 and VCAM1 on tumor endothelial cells, leading to increased T cell infiltration." (PMID 32752264, 2020). "In addition, IHC staining revealed that TGF-β1, BMP4, ICAM1, and VCAM1 expression was decreased in the ARNTL2-knockdown xenograft tumor tissues." (PMID 32826856, 2020). "Interaction of endothelial VCAM-1 with tumor cell VLA-4 and/or endothelial ICAM-1 with platelet αIIbß3 triggers an “outside-in” signaling cascade in endothelial cells that induces the digestion of tight junctions, cytoskeletal rearrangement, and endothelial retraction." (PMID 33042789, 2020). "CCL5 and VCAM1 have been shown to promote tumor progression and metastasis in ESCC." (PMID 33323552, 2020). "Interestingly, an experimental study showed a significant increase in CD8+ T cell infiltration and tumor rejection following extensive Treg depletion, a finding that might be associated to tumor vasculature normalization, which express increased levels of VCAM‐1 and ICAM‐1 on endothelial cells." (PMID 32620049, 2020). "VCAM-1-dependent motility is essential for the development of tumor metastases." (PMID 32847038, 2020). "Additionally, during tumor migration and angiogenesis, integrins on the surfaces of tumor endothelial cells bind to VCAM-1." (PMID 33202648, 2020).